BRCA1 (BRCA1 DNA repair associated)
Diseases named in the same sentence as BRCA1 in open-access papers (continued):
Sharing a sentence is not in itself a finding about the gene and the disease.
metastatic prostate carcinoma (30 papers, 2017 to 2025). A carcinoma that arises from the prostate gland and has spread to other anatomic sites. "We have estimated that the prevalence of pathogenic BRCA1/2 variants in Portuguese patients with metastatic prostate cancer subject to universal testing is 3.1% (95% credibility interval 0.3-10.3%)." (PMID 40051948, 2025). "We have, for the first time, published an estimate of the prevalence of BRCA1/2 pathogenic variants in Portuguese patients with metastatic prostate cancer." (PMID 40051948, 2025). "Thus, our objective was to determine the prevalence of somatic BRCA1/2 variants in Portuguese patients with metastatic prostate cancer by analyzing preliminary data from a prospective clinical trial - the Mainstreaming project." (PMID 40051948, 2025). "Genomic screening in apparently healthy men may represent an opportunity for intervention through increased prostate surveillance, given the recently recognized contribution of germline BRCA1/2 variants to metastatic prostate cancer burden." (PMID 31892343, 2019). "The recent approval of olaparib has paved the way to precision medicine for the treatment of metastatic prostate cancer with PARP inhibitors in this subset of patients, especially in the case of BRCA1 or BRCA2 pathogenic/likely pathogenic variants." (PMID 38731844, 2024). "The current Canadian Urological Association guidelines recommend that germline testing be performed in metastatic prostatic cancer patients and genomic profiling of the tumor in mCRPC patients should be performed while BRCA1/2 are among the targeted genes." (PMID 39796671, 2024). "Based on this evidence, a referral for BRCA1/BRCA2 testing was proposed for men with metastatic prostate cancer." (PMID 37240284, 2023). "In metastatic prostate cancer, an expanded HRD panel included patients with mutations to BRCA1, BRCA2, ATM, FANCA, CHEK2, PALB2, NBN, or HDAC2." (PMID 35205643, 2022). "Approximately 23% of metastatic prostate cancers harbor mutations in DNA-Damage Repair (DDR) genes, including BRCA2, BRCA1, ATM, CDK12, or PALB2 among others." (PMID 33625671, 2021). "However, a bone marrow aspirate revealed metastatic prostate carcinoma, and genetic testing for BRCA1/2 was performed on the collected EDTA sample." (PMID 39907157, 2025). "Although the detrimental impact of prolonged tissue storage on nucleic acid quality is widely acknowledged, our study provides a real-world, multicentre validation specifically within the context of BRCA1/2 testing in metastatic prostate cancer on a large cohort of samples." (PMID 40427202, 2025). "Some, but not all, TNBC and early metastatic prostate cancers are associated with germline variants in BRCA1, BRCA2, and other genes involved in HR DNA repair." (PMID 38837893, 2024). "Of 24 105 patients with metastatic prostate cancer, 443 male patients (median [IQR] age, 72 years) had mCRPC with BRCA1/2 alterations and were eligible and included in our analysis." (PMID 41037269, 2025). "There were 280 metastatic prostate cancer samples tested with 11 (4%) somatic BRCA2 and 7 (2.7%) somatic ATM identified with 1 somatic BRCA1." (PMID 40046829, 2025). "The importance of providing molecular information on the BRCA1 and BRCA2 genes is widely recognized, especially for patients with metastatic prostate cancer." (PMID 39335746, 2024). "In this study, we compiled BRCA1/2 and HRR sequencing data of 197 cases of primary and metastatic prostate cancer." (PMID 39172235, 2024). "Tumor testing for BRCA1 and BRCA2 is recommended for patients with metastatic prostate cancer, also considering a broad panel to guide decisions and genetic counseling." (PMID 33625671, 2021).
metastatic prostate carcinoma (continued). "Even if there is a signal for non-metastatic prostate cancer in BRCA1, this may not justify PSA screening, given the high rates of overdiagnosis." (PMID 40046829, 2025).
ductal carcinoma in situ (29 papers, 1996 to 2026). "Another study provided general guidelines for CPM by calculating the lifetime risk of CBC based on a published systematic review of age at first BC, BRCA1/2 gene mutation, family history of BC, ER status, ductal carcinoma in situ, and oophorectomy." (PMID 31847907, 2019). "BRCA2 carriers were more likely to be diagnosed with ductal carcinoma in situ (18.5% vs. 4.4%, p < 0.001) compared to BRCA1 carriers." (PMID 40275390, 2025). "A patient with progression had a grade 3 lesion with a high-grade ductal carcinoma in situ, potentially suggesting non-BRCA1-mutated TNBC, as BRCA1-positive TNBC typically responds better to platinum agents." (PMID 40443638, 2025). "Thirty-four cases of ductal carcinoma in situ (DCIS) of the breast, with or without associated benign or invasive disease, were analysed for allelic imbalance (AI) in the region of the BRCA1 gene." (PMID 8605099, 1996). "In a cohort of 4573 high-risk women (954 BRCA1 carriers, 598 BRCA2 carriers, 3021 BRCA1/2 non-carriers) and 14,142 rounds with MRI between 2006 and 2015, 221 primary BCs (185 invasive, 36 ductal carcinomas in situ [DCIS]) were diagnosed within 12 months of annual screening." (PMID 38536530, 2024).
hepatocellular carcinoma (29 papers, 2006 to 2026). A malignant tumor that arises from hepatocytes. "AZD.2281 was initially found hypersensitive on BRCA1-deficient breast and hepatocellular carcinoma cell lines." (PMID 35097120, 2022). "In their study, BRCA1 knockout fibroblasts were more susceptible to exosomes isolated from the serum of patients with various tumor locations (colorectal cancer [CRC], hepatocellular carcinoma [HCC], pancreatic cancer [PC], and ovarian cancer)." (PMID 38667297, 2024). "In hepatocellular carcinoma, BRCA1 expression level is positively correlated with the infiltration levels of immune cells including B cells, CD8+ T cells, macrophages and dendritic cells." (PMID 33611848, 2021). "The association between pathogenic mutations in BRCA1 and BRCA2 and other gastrointestinal tumors such as colorectal, gastric cancers, cholangiocarcinoma and hepatocellular carcinoma is unclear." (PMID 33198203, 2020). "Regarding hepatocellular carcinoma (HCC), evidence about its link with BRCA1 and BRCA2 mutations is extremely limited." (PMID 33198203, 2020). "Using a model of chemically induced hepatocellular carcinoma in mouse liver, we comparatively analyzed the dynamics of transcript levels for several genes (BRCA1, BRCA2, CHEK1, CHEK2, ATM, CDK12) in paired samples of normal and tumor tissue over a 24-h PMI using RT-qPCR." (PMID 42073491, 2026). "The observed decrease in BRCA1 expression among older adults may signify a reduced ability for DNA repair in the liver, potentially contributing to age-related liver disorders such as cirrhosis or hepatocellular carcinoma." (PMID 40546347, 2025). "For example, absence of PKM2 accelerates tumor formation in a Brca1-loss-driven model of breast cancer, in a mouse model of medulloblastoma, and results in spontaneous hepatocellular carcinoma (HCC) development in aged mice, indicating that PKM2 negatively regulates tumorigenesis." (PMID 30487597, 2019). "FAD induces caspase-dependent apoptosis through an increase in BAX and cleaved caspase-3 and a decrease in BCL2, RAB51, BRCA1, and MDC1 in hepatocellular carcinoma." (PMID 39765861, 2024). "Moreover, Sorafenib, a standard treatment for hepatocellular carcinoma, increased the sensitivity of TNBC cells to Olaparib by promoting TRIM21-mediated ubiquitination degradation of BRCA1." (PMID 37864041, 2023). "Brca1 mediates the inflammatory response between no-tumor hepatitis/cirrhotic tissues and hepatocellular carcinoma." (PMID 36386298, 2022). "Our qRT-PCR analyses revealed that the mRNA expression levels of MAGEA-3, MAGEA-1, p16, and p15 were significantly increased in the hepatocellular carcinoma HepG2 cell lines after treatment with 10 nM DAC for 72 h and that the RASSF1A and BRCA1 levels were unchanged." (PMID 24963497, 2014).
lymphoma (28 papers, 2007 to 2025). A malignant (clonal) proliferation of B- lymphocytes or T- lymphocytes which involves the lymph nodes, bone marrow and/or extranodal sites. "For example, mutations affecting the loading of RAD51 show a strong predisposition to lymphomas, whereas mutation of Brca1, which affects resection, induces a larger type of tumor." (PMID 33923105, 2021). "Taken together, level of BRCA1 is important in K562 cell differentiation and BRCA1 mutation (K1183R) discovered in lymphoma patients prevented its translocation into the nucleus in hemin-treated K562 cells and eventually disrupted K562 cell differentiation." (PMID 32826945, 2020). "Surprisingly, among BRCA1 mutation(s) discovered in lymphoma patients, BRCA1 K1183R prevented its translocation into the nucleus, failed to reduce NSD2 protein levels in hemin-treated K562 cells and eventually disrupted cell differentiation." (PMID 32826945, 2020). "Moreover, mutation of BRCA1 at K1183, which are regularly identified during lymphoma, disrupted erythrocyte differentiation by inhibiting NSD2-BRCA1 interaction in hemin-mediated K562 cell differentiation." (PMID 32826945, 2020). "However, the balance between pathway usage could vary between Brca1 mutations, as suggested by mouse phenotypes, where Brca1CC/CC, 53bp1−/− mice have short lifespans and develop lymphoma, whereas Brca1Δ11/Δ11, 53bp1−/− mice have normal life-spans." (PMID 38001070, 2023). "Male relatives of BRCA1 carriers had significantly higher risks of esophageal cancer (RR = 2.33, 95% CI 1= 0.36-4.00; P = 0.002) and lymphoma (RR = 4.77, 95% CI = 1.92-11.86; P = 0.005) than male relatives of non-carriers." (PMID 36861435, 2023). "Conversely, a few studies have suggested that the BRCA genes are associated with increased risk of NHL, HL, or MM including BRCA1 (7.7-fold increase) and BRCA2 (5.9-fold increase) in the Japanese population and BRCA2 (3.3-fold increase) in pediatric or adolescent lymphoma survivors from St." (PMID 40253392, 2025). "HPA examination indicated that BRCA1 is downregulated in lymphoma." (PMID 32826945, 2020). "Importantly, ROSI cotreatment increased PPARγ expression in mammary-derived lymphomas and carcinomas from PPARγ-WT and PPARγ-MG KO mice, but only specifically augmented BRCA1 in PPARγ-WTs." (PMID 25889730, 2015). "Together, these data suggest that the BRCA1-delta11q isoform of BRCA1, which maintains its RAD51 loading activity, provides further evidence that inactivation of BRCA1-mediated RAD51 loading fuels lymphoma development in mice." (PMID 33923105, 2021). "In contrast, the Tr53bp1 and Brca1 double knockout mice that are proficient in DNA end resection but defective for RAD51 loading have reduced lifespan, and the mice that survive to adulthood develop lymphomas." (PMID 33923105, 2021). "Unlike Atm KO mice, there was no defect in TCRβ rearrangement in 1-month-old Brca1−/−;Trp53bp1−/− mice when lymphomas were not developed." (PMID 32139898, 2020).
osteosarcoma (26 papers, 2014 to 2025). A usually aggressive malignant bone-forming mesenchymal neoplasm, predominantly affecting adolescents and young adults. "It has been shown that mutations, genomic instability and loss of heterozygosity resulting in BRCA1/2 inactivation occur in 91% and 78% of osteosarcoma, respectively." (PMID 40104509, 2025). "In osteosarcoma cells, defects in BRCA1/2 make tumors susceptible to the PARP inhibitor talazoparib." (PMID 33198792, 2020). "Nevertheless, it was reported that up to 80% of osteosarcoma patient samples exhibit a “BRCAness,” indicating that they share similarities to tumours harbouring germline mutations in BRCA1 or BRCA2 making them deficient in DNA repair pathways." (PMID 32961800, 2020). "This study has also shown that the expression of PARP1, γH2AX, BRCA1/2 are significantly associated with RFS of osteosarcoma patients." (PMID 29784019, 2018). "In our study, as predicted, the expression of the PARP1-H2AX pathway and preservation of BRCA1/2 expression was associated with shorter survival of osteosarcoma patients." (PMID 29784019, 2018). "In addition, temozolomide, SN-38, and doxorubicin synergized with talazoparib in osteosarcoma cell lines bearing molecular features of BRCA1/2-mutated tumors." (PMID 36430819, 2022). "However, the mutational make-up of osteosarcomas is versatile, as some osteosarcomas also present with molecular signatures reminiscent of BRCA1/2 deficient tumors." (PMID 28484590, 2017). "Herein, we describe the case of a 28-year-old man diagnosed with the primary cutaneous osteosarcoma with decreased copy number of BRCA1 and BRCA2, based on histological morphology, immunohistochemical examination, and germline testing." (PMID 40104509, 2025). "Prevention strategies of this condition are different from the one used for BRCA1/2 mutation carriers, since LFS component tumors also include soft tissue sarcomas, osteosarcoma, brain tumors, and adrenocortical carcinomas." (PMID 37065479, 2023). "In the osteosarcoma dataset of TARGET database, although BAP1 expression was similar in osteosarcoma tissues from patients with different clinicopathologic characteristics, it was positively correlated with BRCA1, CDC6, and CDC45." (PMID 36003792, 2022). "This analysis yielded scarHRD scores clearly lower than those detected for BRCA1,2-mutated cell lines for all osteosarcoma lines and absence of a significant difference between RB1-defective and RB1-normal osteosarcoma groups." (PMID 34862364, 2021). "PARP1, γH2AX, BRCA1, and BRCA2 are found in the nuclei of osteosarcoma tumours, and poor survival in osteosarcoma patients has been linked to expression of these factors." (PMID 32961800, 2020). "The expression patterns of PARP1, γH2AX, BRCA1, and BRCA2 were significantly associated with shorter survival of osteosarcoma patients." (PMID 29784019, 2018). "In clinical tissue samples, the expression of PARP1, γH2AX, BRCA1, and BRCA2 were closely associated with each other and their expression patterns were correlated with advanced clinical indicators of osteosarcoma such as higher stage, latent distant metastasis, and higher histological grade." (PMID 29784019, 2018). "The variables included in multivariate analysis for the 35 osteosarcomas were the factors significantly associated with OS or RFS: age, tumor size, tumor stage, distant metastasis, histologic grade, and the expression of PARP1, γH2AX, BRCA1, and BRCA2." (PMID 29784019, 2018). "However, >80% of osteosarcomas exhibit a specific combination of single-base substitutions, LOH, or large-scale genome instability signatures characteristic of BRCA1/2-deficient tumours." (PMID 26632267, 2015). "Interestingly, the osteosarcomas carried large-scale genome instability signatures characteristic of BRCA1/2-deficient tumors, and no one specific mutation was responsible for the majority of osteosarcomas." (PMID 38962713, 2024).
osteosarcoma (continued). "In low-stage osteosarcomas, tumor stage (OS; P = 0.036, RFS; P = 0.025), histologic grade (OS; P = 0.036, RFS; P = 0.025), γH2AX expression (OS; P = 0.009, RFS; P = 0.006), and BRCA1 expression (OS; P = 0.026, RFS; P = 0.005) was associated with both OS and RFS." (PMID 29784019, 2018). "Because the individual and combined expression patterns of PARP1, γH2AX, BRCA1, and BRCA2 were significantly associated with advanced clinicopathologic factors and survival of osteosarcoma patients, we evaluated the effects of PARP inhibition on the survival of osteosarcoma cells." (PMID 29784019, 2018). "The expression of PARP1, γH2AX, BRCA1, and BRCA2 were grouped as positive in 74% (26 of 35 of cases), 57% (20 of 35 of cases), 49% (17 of 35 of cases), and 46% (16 of 35 of cases) of osteosarcomas, respectively." (PMID 29784019, 2018). "Based on this rationale, this study might also be helpful for the selection of osteosarcoma patients that could potentially benefit from anti-PARP therapy, especially those in the poor-prognostic subgroup of osteosarcomas expressing PARP1, γH2AX, or BRCA1/2." (PMID 29784019, 2018). "This study suggests that combined use of a PARP inhibitor with doxorubicin, a DNA damaging agent, might be effective in the treatment of osteosarcoma patients, especially in the poor-prognostic subgroups of osteosarcoma expressing PARP1, γH2AX, or BRCA1/2." (PMID 29784019, 2018). "In conclusion, this study demonstrated that the individual and combined expression patterns of PARP1, γH2AX, BRCA1, and BRCA2 might be useful for the prediction of survival of osteosarcoma patients." (PMID 29784019, 2018). "Moreover, when we performed addition analysis on the combined expression patterns of PARP1, γH2AX, BRCA1, and BRCA2, 51% (18/35) of osteosarcomas were included in the poor-prognostic group." (PMID 29784019, 2018). "Therefore, this study evaluates the expression and prognostic significance of the individual and combined expression patterns of PARP1 and PARP1-related DDR molecules such as γH2AX, BRCA1, and BRCA2 in osteosarcomas." (PMID 29784019, 2018). "The onset of the disease may be related to deletion in the BRCA1 and BRCA2 genes, which led to the inability of cells to effectively repair DNA damage, resulting in genomic instability that promoted the occurrence and progression of osteosarcoma." (PMID 40104509, 2025). "Similarly, other BRCA1-wild type cell lines tested, such as the non-tumour MCF10A breast cell line, the lung fibroblastic MRC5 cell line (data not shown) and the U2OS osteosarcoma cell line showed no particular sensitivity to PARG depletion." (PMID 27375368, 2016).